PRKACG (protein kinase cAMP-activated catalytic subunit gamma)
Description:
Phosphorylates a large number of substrates in the cytoplasm and the nucleus.
Synonyms: PKACg; BDPLT19; KAPG
Tractability: Small molecule: a drug acting on it is in phase 1 trials; a high-quality ligand is known; it belongs to a druggable protein family. PROTAC: ubiquitination databases record sites on it; a small molecule that binds it is known.
Target class: Kinase; AGC protein kinase PKA family; Protein Kinase; AGC protein kinase group; Enzyme
Gene: Protein-coding gene on chromosome 9 (69,012,504 to 69,014,113, reverse strand). Ensembl gene ENSG00000165059.
Subcellular location (Human Protein Atlas): Cytosol; Basal body; Cytokinetic bridge; Microtubules; Primary cilium
Pathways (Reactome):
Signal Transduction: DARPP-32 events; Degradation of GLI1 by the proteasome; Degradation of GLI2 by the proteasome; GLI3 is processed to GLI3R by the proteasome; GPER1 signaling; Hedgehog 'off' state; MAPK6/MAPK4 signaling; PKA activation; PKA-mediated phosphorylation of CREB; VEGFA-VEGFR2 Pathway
Metabolism: Glucagon-like Peptide-1 (GLP1) regulates insulin secretion; PKA activation in glucagon signalling; PKA-mediated phosphorylation of key metabolic factors; Regulation of glycolysis by fructose 2,6-bisphosphate metabolism; Regulation of insulin secretion; Triglyceride catabolism
Developmental Biology: RET signaling; ROBO receptors bind AKAP5
Disease: ADORA2B mediated anti-inflammatory cytokines production; FCGR3A-mediated IL10 synthesis
Immune System: CD209 (DC-SIGN) signaling; Rap1 signalling
Transport of small molecules: HDL assembly; Vasopressin regulates renal water homeostasis via Aquaporins
Cellular responses to stimuli: High laminar flow shear stress activates signaling by PIEZO1 and PECAM1:CDH5:KDR in endothelial cells
Hemostasis: Factors involved in megakaryocyte development and platelet production
Neuronal System: CREB1 phosphorylation through the activation of Adenylate Cyclase
Gene Ontology:
Molecular function: potassium channel inhibitor activity; protein binding; cAMP-dependent protein kinase activity; protein kinase A regulatory subunit binding; protein serine/threonine kinase activity; ATP binding; protein kinase activity; protein serine kinase activity
Biological process: adenylate cyclase-activating G protein-coupled receptor signaling pathway; high-density lipoprotein particle assembly; male gonad development; positive regulation of insulin secretion; renal water homeostasis; spermatogenesis; vascular endothelial cell response to laminar fluid shear stress
Cellular component: cAMP-dependent protein kinase complex; ciliary base; cytosol; nucleoplasm; nucleus
Genetic constraint (gnomAD): Loss-of-function variants: 24 observed, 26.79 expected, observed/expected ratio (o/e) 0.9, 90% interval 0.65 to 1.26. The upper end of that interval is the gene's LOEUF score, 1.26, which puts it in group 5 of 6, group 1 being the genes least tolerant of losing a copy. Missense variants: 481 observed, 483.35 expected, observed/expected ratio (o/e) 1, 90% interval 0.92 to 1.07. Synonymous variants: 202 observed, 208.73 expected, observed/expected ratio (o/e) 0.97, 90% interval 0.86 to 1.09.
Gene-disease validity (ClinGen):
ClinGen rates the evidence that PRKACG causes each of these diseases.
platelet-type bleeding disorder 19 (autosomal recessive): Disputed. Any isolated hereditary giant platelet disorder in which the cause of the disease is a mutation in the PRKACG gene.
Homologues: Orthologues: chimpanzee PRKACG (99% identical), macaque PRKACG (90% identical), tropical clawed frog prkaca (78% identical), zebrafish prkacab (78% identical), zebrafish prkacba (72% identical), Drosophila melanogaster CG12069 (44% identical), Drosophila melanogaster Pka-C2 (43% identical), zebrafish prkg3 (40% identical), Drosophila melanogaster Pkg21D (38% identical), Caenorhabditis elegans egl-4 (36% identical). Paralogues in human: PRKACA (82% identical), PRKACB (77% identical), PRKX (44% identical), PRKG2 (42% identical), PRKG1 (42% identical).
Diseases named in the same sentence as PRKACG in open-access papers:
PRKACG is named in the same sentence as 14 diseases in open-access papers, as found by Europe PMC text mining. Sharing a sentence is not in itself a finding about the gene and the disease. The quoted sentences say what the papers report.
breast carcinoma (3 papers, 2014 to 2022). "Our findings suggest that PPP1CA, PRKACG and PRKAR1B are associated with breast cancer–specific survival." (PMID 33991172, 2021). "PKA and PP1 subunit mRNA was also assessed; PPP1CA, PRKACG and PRKAR1B were associated with breast cancer–specific survival." (PMID 33991172, 2021). "PRKACG, PRKAR1B and PPP1CA were the most strongly and reproducibly associated with breast cancer–specific survival." (PMID 33991172, 2021). "PKA and PP1 subunit mRNA expression was also assessed; PPP1CA, PRKACG and PRKAR1B were associated with breast cancer–specific survival." (PMID 33991172, 2021).
Alzheimer disease (1 paper, 2024). A progressive, neurodegenerative disease characterized by loss of function and death of nerve cells in several areas of the brain leading to loss of cognitive function such as memory and language. "Conversely, for hub genes identified from upregulated DEGs, Alzheimer’s disease has been linked to CD2, CDC25A, CKS2, LCK, PRKACG, and S100A7." (PMID 39766348, 2024).
Macrothrombocytopenia (1 paper, 2025). "Another case involved a genetic defect in the PRKACG gene, associated with macrothrombocytopenia." (PMID 39653062, 2025).
papillary carcinoma (1 paper, 2022). A malignant epithelial neoplasm characterized by a papillary growth pattern. "ERBB3/ERBB4/RAF1 kinases were activated in papillary carcinoma compared to other variants, PAK3/PAK6/CDK1 kinases were activated in NOS, and PRKACA/PRKACB/PRKACG kinases were activated in differentiation variants." (PMID 35659036, 2022).
skin cancer (1 paper, 2022). "Again there are no previous publications on skin cancer and PRKACG association, and repeated analyses in a larger cohort would be needed to confirm this possible association between the PRKACG gene and skin cancer." (PMID 35505292, 2022).
cancer (5 papers, 2014 to 2024). A tumor composed of atypical neoplastic, often pleomorphic cells that invade other tissues. "PRKACG is a gene that encodes the protein kinase A subunit Cγ, whose role in cancer has not been elucidated." (PMID 35477453, 2022).
tumours (1 paper, 2020). "Comparison of the laBCC tumours before systemic treatment with localised BCC tumours yielded a significant differential expression of three genes of the Hh pathway: GAS1, GLI similar 2 (GLIS2), and protein kinase CAMP-activated catalytic subunit gamma (PRKACG) (P < 0.05)." (PMID 31988301, 2020).
PRKACG also shares sentences with these, for which no sentence is quoted: acute myeloid leukemia (1 paper); COVID-19 (1); gallbladder cancer (1); hearing loss (1); lung carcinoma (1); renal cell cancer (1); Thrombocytopenia (1).